CD44 (CD44 molecule (IN blood group))
Diseases named in the same sentence as CD44 in open-access papers (continued):
Sharing a sentence is not in itself a finding about the gene and the disease.
tumor (continued). "There is growing evidence that CTC population is extremely heterogeneous, with a small percentage of tumor cells, called cancer stem cells (CSCs) expressing CD44, ALCAM, POU5F1B, able to proliferate and form new tumors." (PMID 31552188, 2019). "The CD44+ SKOV3 cell lines were targeted by hyaluronic acid-paclitaxel (HA-TXL) which resulted in decreased tumor weight and nodules." (PMID 31810474, 2019). "The novel finding that rhPRG4 opposes HAS2 and CD44 induction by TGFβ has implications for downregulating the tumor promoting roles, while maintaining the tumor suppressive aspects of TGFβ actions." (PMID 31361756, 2019). "We found that ALDH+ cells are mainly localized in the tumor interior, whereas CD44+/CD24− cells are enriched at the tumor’s invasive edge." (PMID 30659204, 2019). "Most tumor sphere cells were CD44 + CD24-, while only 1.16 ± 0.95% parental cells were CD44 + CD24-." (PMID 31196164, 2019). "Accordingly, the suppression of WNT/β-catenin signaling decreased the ALDH1+ and CD44+/CD24low population inhibiting tumor growth and metastatic ability." (PMID 31619007, 2019). "This should be attributed to their active targeting ability mediated by the specific binding of HA with CD44 over-expressed by MCF-7/ADR tumor." (PMID 31623608, 2019). "Overexpression of CD44 on cancer cells augments tumor aggressiveness by increasing adhesion to its extracellular matrix ligand HA." (PMID 30943985, 2019). "We observed similar results with treated TU-BcX-2 K1 spheres derived from tumor explants – romidepsin resulted in a suppression of the CSC phenotype (CD44+CD24−) while Taxol maintained stemness." (PMID 30845999, 2019). "The tumor sphere cells isolated from 4 T1 parental cells were CD44 + CD24-, while parental cells were CD44 + CD24+." (PMID 31196164, 2019). "Circulating Gal-3 can also increase tumor cell adhesion to and migration across the endothelium by interacting with MUC1 on tumor cells, leading to exposure of additional glycosylated ligands including CD44 that bind E-selectin on endothelial cells." (PMID 31195728, 2019). "In vivo results indicated that the interaction between HA and CD44 receptor dramatically improved the accumulation of the nanovector in CD44-positive tumor, leading to high gene expression." (PMID 30943985, 2019). "MiR-199a also prevents the tumor growth and increases the sensitivity toward Cisplatin, Paclitaxel, and Adriamycin through down regulation of CD44 in ovarian CSCs." (PMID 31810474, 2019). "Control tumour sections exhibited a strongly positive CD44 labelling while tumour sections bellonging to the treatment groups displayed weak CD44 staining consistent with the antitumour effect produced by PRP treatment." (PMID 31388092, 2019). "As it can be seen throughout this review, HA-based polymeric nanocarriers are an attractive system for biomedical applications, mainly anticancer therapy due to recognition of HA by CD44, which allows active targeting towards certain tumor cells." (PMID 31311150, 2019). "Together with the tumor stem cell markers, CD44 and CD133, AC were found also to express the paracrine factors, BMP4, FGF, and SHH." (PMID 31191748, 2019). "Another group developed self-assembled tumor-targeting HA–IR–780 nanoparticles for PTT in a CD44-over-expressed orthotopic bladder cancer model." (PMID 31266194, 2019). "Evaluation of the tumor cell surface-marker expression in the ascites generated from CD105(+) cell injections demonstrated expression in >98% CD105(+)/CD73(−)/CD44(−) of cells." (PMID 31684072, 2019). "It is known that HA binding to certain isoforms of CD44 selectively activates multiple oncogenic signaling pathways leading to tumor cell-specific phenotypes." (PMID 31293964, 2019). "Transfer of as few as 100 CD44+CD24−/low cells resulted in tumor formation, whereas the transfer of thousands of other cells with various phenotypes did not." (PMID 31137841, 2019).
tumor (continued). "Administration of an LSD1 inhibitor hampered tumor growth, but the most significant finding was that it also led to a pronounced reduction of the stem-like CD44+CD24-/low subpopulation." (PMID 31627418, 2019). "CD44 mean percentage positive epithelial cells were significantly higher in tumour and distal tissue compared to normal tissues (41.77 ± 4.234, P = 0.0017) and (39.24 ± 9.362, P = 0.0439) vs (14.95 ± 3.961) respectively." (PMID 30950180, 2019). "In other works, chitosan/siRNA polyplexes have been coated with hyaluronic acid to increase the targeting of CD44+ tumor endothelial cells (by 2.1-fold) and to improve haemocompatibility for intravenous administration." (PMID 31311176, 2019). "This stromal IL-7 provides CD44-positive colon cancer cells with further increased tumor-initiating ability, thereby promoting tumor cell growth both in vitro and in vivo." (PMID 31067787, 2019). "Tumor expression profile included an upregulation of basal cell markers such as Krt5, Krt6, Krt14 and Krt1 as well as Cdh3 and Cd44." (PMID 31779626, 2019). "Since Mucin13 and CD44 were well-known central players in tumor metastasis, we chose the two molecules to clarify the role of Rab14-positive vesicle in metastasis regulated by CHML." (PMID 31175290, 2019). "The expression level of CD44 was also significantly correlated with tumor size, tumor stage, and gender (P=0.001, 0.035, and 0.05 respectively)." (PMID 31341476, 2019). "To confirm the effect of CC-CAFs on tumor metastasis and the role of CD44 in vivo, we injected SW48 cells alone, CC-CAFs alone, SW48 cells mixed with CC-CAFs or SW48-shCD44 mixed with CC-CAFs via spleen capsule and tail vein." (PMID 31367190, 2019). "oHA‐DOX@MSNs/HAP shows much higher efficiency cellular uptake and drug release in tumor regions due to more effective CD44 targeting of oHA." (PMID 31380195, 2019). "HMW-HA blocks proliferation by signaling through CD44 to promote G1/G0 arrest and alter tumor growth kinetics by suppressing neo-angiogenesis and immune responses." (PMID 31134064, 2019). "Taken together, this study shows that CD44 has an important role in arresting HA around tumor cells, having a significant effect on tumor cell HA content independent on levels of HA synthesis." (PMID 30909497, 2019). "In our study, CD44 expression was detected in tumor cells in 26 of 30 pre-treatment samples and was similar before and after chemotherapy." (PMID 30999901, 2019). "Many evidences indicated that CD44 expression is strongly associated with epithelial-mesenchymal transition (EMT) and cancer stem cell (CSC) phenotypes such as tumor invasion, metastasis, recurrence, or chemoresistance." (PMID 31049070, 2019). "In concordance with above findings, immunohistochemistry also showed a significant enrichment for CD133 and CD44 in tumour and distal tissues." (PMID 30950180, 2019). "Although, dissociated tumor cells from co-treated SKOV3 xenografts significantly reduced the proportion of CD44 population (4.97%) and ALDH (2.05%) activity in these tumors, these proportions remained higher in the controls and monotherapy treated tumors." (PMID 31470883, 2019). "In vitro studies showed a CD44-dependent cellular uptake and consequently a greater internalization of nanogels in tumor cell lines that overexpress CD44 receptor." (PMID 31408954, 2019). "miR-34a was reported to be repressed in CD44+ prostate CSCs, below levels of let-7b, a previously reported tumor suppressive microRNA." (PMID 30860027, 2019). "CD44 is an integral membrane glycoprotein that binds to hyaluronic acid and is involved in tumor growth and metastasis." (PMID 30992079, 2019). "We previously showed a significant correlation between CD44 expression and tumor grade and depth of invasion." (PMID 30992079, 2019).
tumor (continued). "The active tivantinib as a single agent showed strong inhibition of various tumor-promoting signaling molecules, such as reduced RalB, CD44, c-Myc, and Id1 as well as inhibition of Akt activation, whereas the inactive enantiomer did not elicit much effect." (PMID 31100813, 2019). "CD44 is considered a cancer stem cell marker in many tumor types and has been shown to signal through multiple pro-cancer pathways, including Ras/MAPK, PI3K/Akt, and Rho GTPases." (PMID 31762938, 2019). "On the other hand, except metabolism, the derived genes are also associated with distinct modes of tumor physiology in CRC, such as detoxification (GSTP1), metastasis (KIT), immunomodulation & stem cell renewal (CD44) and ER stress (CCT7)." (PMID 30809322, 2019). "As a member of the cell adhesion molecule family, CD44 plays a crucial role in tumor growth and motility." (PMID 31598171, 2019). "CD44 isoforms have also been detected in cancer stem cells (CSCs) which appear to display unique ability to initiate tumor cell-specific properties." (PMID 31293964, 2019). "For example, the tumor suppressor miR-223 is downregulated in CD44+CD24−/low triple-negative breast CSCs, and its overexpression resensitized the cells to induction of apoptosis." (PMID 31137841, 2019). "Immunocytochemistry staining showed the CD44 expression in tumor spheres of CD44+ BxPC-3 and PANC-1." (PMID 31049070, 2019). "A higher level of CD44 expression in CRC liver metastases compared with primary tumor was observed by immunofluorescence." (PMID 31367190, 2019). "In some tumor cells, CD44-ICD has been reported to function as a signaling molecule that translocates into the nucleus and activates transcription." (PMID 31624271, 2019). "We have found that expression of the CSC-associated markers CD44 and ALDH1A is significantly increased in tumor cells with mutated or down-regulated BRCA1." (PMID 31273285, 2019). "Previous studies have reported that CD44 is proteolytically cleaved in a number of tumor cell types and chondrocytes in OA patients." (PMID 31624271, 2019). "L-161,982 also reduced expression of the colonic stem cell markers, CD133 and CD44, and inhibited tumor sphere formation." (PMID 30894570, 2019). "HA binding receptor, CD44 is a transmembrane glycoprotein and has been detected in both normal and tumor cells." (PMID 31293964, 2019). "In a murine xenograft model, Fap1 inhibition was associated with decreased tumor growth, delayed progression after oxaliplatin, decreased relative abundance of CD133+CD44+ cells, and phosphorylation of Fap1 substrates (Fas and Gsk3β)." (PMID 29899829, 2018). "On univariate analysis, only EGFR staining at >50% of tumour cells (HR = 3.57, p = 0.038) and CD44 staining at 3+ intensity (HR = 7.99, p = 0.004) were associated with a poorer overall survival." (PMID 29731973, 2018). "Gemcitabine induced PCSC overexpressing ABCB1 and CD44+ that correlated with higher tumor histological grade and worse prognosis." (PMID 30004402, 2018). "The expression of CD44 was found to be correlated withsurvival, tumor size, stage and metastasis in GC." (PMID 29845783, 2018). "Both cell fractions are tumour-initiating and both express high levels of CD44 but the CSCs with an epithelial phenotype express high levels of ESA whereas those that have undergone EMT have low or absent levels of ESA." (PMID 29568372, 2018). "In 2007, Prince and colleagues first reported the existence of a subpopulation of HNSCC cells, isolated by expression of the cell-surface protein CD44, in primary tumor samples." (PMID 29861860, 2018). "ALDH1 was mainly expressed in the cytoplasm, whereas the CD44 staining was mainly on the cell membranes of tumor cells, as expected based on the usual distribution." (PMID 30372483, 2018). "HA is an abundant component of the matrix that modulates immune cells, by interactions with TLRs and CD44, and influences tumor growth via regulation of cellular differentiation and angiogenesis." (PMID 29970158, 2018).
tumor (continued). "These two viruses were able to kill the CSCs in vitro and showed significant anti-tumor effect against CD44+CD24−/low–derived xenografts." (PMID 29671772, 2018). "Here, the three tumor cell lines evaluated showed high levels of CD44 expression, detecting two different populations (with low and high expression)." (PMID 30564299, 2018). "It is worth mentioning that even though ALDH+ cells have also been identified as tumor initiating cells, they partially overlap the isolated CD44+/CD24− population, indicating that the phenotypically isolation of cells does not include all BCSCs." (PMID 30200262, 2018). "To support this, we also found that A2780-M cells express higher levels of CD133 and CD44, biomarkers for tumor stem cells." (PMID 30046596, 2018). "RAB39A knockdown in 143B tumor cell population also impaired the expression of the stem cell marker CD44 compared to control (shCont) cells." (PMID 29515775, 2018). "With co-expression staining based on flow cytometry data, we found a detectable population of CD44+/CD24low tumor cells in circulation." (PMID 29854878, 2018). "Knocking down OPN significantly inhibited the sphere formation and stemness-related genes expression, and delayed tumor initiation of CD133+/CD44+ subgroup of HCC cells." (PMID 30064482, 2018). "Many types of delivery systems containing HA as a targeting molecule for CD44 were established to increase intracellular drug concentrations in tumor tissue." (PMID 29899207, 2018). "Very recent studies have interpreted the crucial events on interactions of HA with its cellular receptor CD44 regulating the progression of tumor." (PMID 29890947, 2018). "CD44 was stained immunohistochemically as a marker of stemness and showed strong circular membranous staining in tissue from both primary tumor and metastasis." (PMID 29693014, 2018). "In primary human bladder cancer, a marked expression of CD47 was seen in CD44+ tumor initiating cells (TICs) that escape phagocytosis." (PMID 30200242, 2018). "In this study, PET imaging with the novel anti-CD44 monoclonal antibody RG7356 confirmed tumour uptake for patients receiving ≥ 450 mg." (PMID 29356983, 2018). "Consistently, both cells also demonstrated several cancer stem-like features including the increased percentage of CD44+ and side-population cells as well as the enhanced ability to generate tumor spheres." (PMID 30005681, 2018). "In contrast, the proportion of effector memory cells (CD44+CD62L−) in CD8+ populations was lower in FASNhigh tumor than in FASNlow tumor." (PMID 30619288, 2018). "Further studies indicated that treatment with neutralizing anti-CD44 antibodies reduced tumor burden on the peritoneal wall and diaphragm in a xenograft mouse model, suggesting that targeting CD44 is a promising approach for the reduction of peritoneal tumor." (PMID 30445726, 2018). "In a human-in mouse model, we previously showed that breast CD44+CD24− CSCs were present in the primary tumor, with a mesenchymal phenotype allowing them to migrate towards bone." (PMID 29461491, 2018). "An MMP-14/CD44/Snail axis has been previously identified as an important regulator of tumor invasion in other tumors." (PMID 30034628, 2018). "In our model, fibroblasts were characterized by a significant decrease in S100a4 and a significant increase in Cd44 expression following co-culture with tumor cells in 3D." (PMID 29435153, 2018). "Patients with enhanced AR or let-7a expression predicted a better prognosis, while the tumor cells with CD44+/CD24-/low phenotype predicted a worse prognosis index." (PMID 29423076, 2018). "The higher expression of CD44 in the tumor periphery compared to the tumor core (high P/C ratio for CD44 expression) was correlated to early tumor progression and short survival of GBM patients." (PMID 30210550, 2018). "These cell-ECM interactions additionally involve binding of HA with receptors such as CD44 and RHAMM which are associated with tumor progression and metastasis." (PMID 30131707, 2018).
tumor (continued). "Tumor cells isolated from the basal-like MDA-MB-231 cell-derived xenografts are predominantly CD44+." (PMID 29510720, 2018). "Thereby, the primary tumor showed the strongest signal of CD44 with a maximum fold change (FC) of 1.29 (false discovery rate, FDR: 0.026%) compared to the metastasis." (PMID 29693014, 2018). "In particular, CD44 expression in GBM enhances the invasion of GBM by promoting tumor cell migration through cell-extracellular matrix interactions." (PMID 30210550, 2018). "Other stem cell markers, such as ALDH1, further enrich the cancer stem cell properties of the CD44 tumor population." (PMID 29652830, 2018). "The cultured GSCs with a high expression of CD44 obtained from the tumor periphery had a high invasive activity that is enhanced by CD44." (PMID 30210550, 2018). "Meanwhile, GAPLINC regulated tumor cell proliferation and migration through competing with CD44 for miR-211-3p." (PMID 30177521, 2018). "There, we have also revealed elevated levels of two forms of CD44 along with increased expression of HA-CD44 mediated downstream effectors like cyclinD1 and β-catenin in HepR21 cells compared to HepG2, having lower tumor potency than HepR21." (PMID 29535843, 2018). "Nonetheless, the CD44+ CSC-like cells continue to be significantly enriched in the hypoxic (EGFP+) population of tumor cells ex vivo from 2nd xenografts derived from either EGFP+ or EGFP− MCF7 cells." (PMID 29510720, 2018). "The released CD44-ICD sufficed to rescue transcriptional enhancement in CD44-negative tumor cells and in cd44-/- MEFs." (PMID 30540779, 2018). "The blockade of CD44 expression avoided the local and metastatic formation of tumor nodules by CD90+ cells." (PMID 29996919, 2018). "We demonstrated that GSCs highly expressing CD44 exist in the invasion niche at the tumor periphery of GBM." (PMID 30210550, 2018). "Immunohistochemical staining and flow cytometry of CD44 and E-cadherin were compared in primary tumor, metastasis, and cell cultures." (PMID 29693014, 2018). "CD44 acts as upstream of the mammalian Hippo signaling pathway (merlin-MST1/2-Lats1/2-YAP-cIAP1/2) and suggests a functional role of CD44 in attenuating tumor cell responses to stress and stress-induced apoptosis." (PMID 29747682, 2018). "Positive expression of MACC1, CD44, and Twist1 was found to be positively correlated with invasion, tumor grades, and lymph- node-metastasis (LNM) stages and tumor-node-metastasis (TNM) stages for patients with CAC." (PMID 30021598, 2018). "These strategies include CD44 neutralizing antibodies, tumor delivery of shRNAs, ectodomain mimics, and aptamers." (PMID 29747682, 2018). "The present double immunostaining study showed that CD44 and Nestin were colocalized at the cell membrane of the tumor cells in the tumor periphery, demonstrating existence of stem cells expressing CD44 in the invasion area." (PMID 30210550, 2018). "CPI-455 attenuated clonal sphere and tumor formation by stem-like cells that highly express JARID1B while also depleting the CD44-positive and Aldefluor-high fractions conventionally used to designate OSCC stem cells." (PMID 29507668, 2018). "By its engagement in exosome biogenesis CD44/CD44v6 contributes to disseminated tumor cell settlement and growth in distant organs." (PMID 30211160, 2018). "All cell types in the tumour expressed CD44, and there was a specific intense membrane staining for CD44 on almost all TiHo-0906 cells." (PMID 30185896, 2018). "The binding of CD44 on migrating tumor cells to CD62 on endothelial cells is responsible for the initial steps of extravasation." (PMID 30200242, 2018). "Effector (CD62L−CD44+Tim-3−) and memory (CD62L+CD44+) CD8± T cells in the tumor possessed higher Eomes expression than naïve T cells (CD62L+CD44−), but lower expression of Eomes than exhausted CD8± TILs (CD62L−CD44+Tim-3+)." (PMID 30619337, 2018).